CCL3 (C-C motif chemokine ligand 3)
Diseases named in the same sentence as CCL3 in open-access papers (continued):
Sharing a sentence is not in itself a finding about the gene and the disease.
endometriosis (10 papers, 2012 to 2023). The growth of functional endometrial tissue in anatomic sites outside the uterine body. "For example, higher follicular MIP-1α (CCL3) and CD44 were correlated with polycystic ovary syndrome and IL-23, IFN-γ, and TNF-α correlated with endometriosis." (PMID 34868029, 2021). "The highly differential genes between the two groups showed that C–C motif chemokine ligand 3 (CCL3) and X-C motif chemokine ligand 1 (XCL1) were significantly elevated in endometriosis while cytotoxic molecules including GNLY, GZMB and GZMH were significantly down-regulated." (PMID 34039410, 2021).
experimental autoimmune encephalomyelitis (10 papers, 2011 to 2024). An autoimmune demyelinating disease of the central nervous system that is produced experimentally in animals by the injection of homogenized brain or spinal cord in Freund's adjuvant. "MCP-1/CCL2, IL-8 and MIP-1α/CCL3 have been demonstrated to be important pro-inflammatory mediators involved in the pathogenesis of experimental autoimmune encephalomyelitis (EAE) and MS." (PMID 35309326, 2022). "It has been reported in experimental autoimmune encephalomyelitis that mononuclear cell infiltration in the acute disease and the relapse phase is controlled by CCL3 or CCL2, respectively, suggesting a distinct functional differentiation of both chemokines." (PMID 26640428, 2015). "Moreover, the upregulation of Ccl2, Ccl3, Ccl4, Ccl7, Cxcl9, and Cxcl10 is also related to the acute phase of experimental autoimmune encephalomyelitis." (PMID 35911717, 2022). "Lif KO animals have increased expression of CXCL1, GM-CSF, RANTES/CCL5 and MIP-1β/CCL3 early during an experimental autoimmune encephalomyelitis model and reduced CCL2, CCL3, and CXCL10 at a later stage of the disease." (PMID 25277705, 2014). "Furthermore, combined neutralization of all three known CCR5 ligands (CCL3, CCL4, CCL5) has been shown to ameliorate the course, i.e., reduce disease activity, in MS animal models of experimental autoimmune encephalomyelitis." (PMID 33324890, 2019). "CXCL10/IP-10, CCL2/MCP-1, CCL3/MIP-1a, CCL4/MIP-1b, CCL5/Rantes, CCL7/MCP-3 and CXCL9/Mig are among the described proinflammatory chemokines produced by immune cells and CNS glia in MS and in the animal model of MS, experimental autoimmune encephalomyelitis (EAE)." (PMID 26039252, 2015).
heart failure (10 papers, 2013 to 2026). Inability of the heart to pump blood at an adequate rate to meet tissue metabolic requirements. "DNMT3A mutated monocytes from patients with heart failure have been shown to express higher mRNA levels of IL-1β, IL-6 and IL-8, macrophage inflammatory chemokines CCL3 and CCL4 and the inflammasome NLRP3." (PMID 36835370, 2023). "Circulating levels of CCL3 (as well as CXCL10 and CD40 ligands) were associated with heart failure." (PMID 36769452, 2023). "Based on the inflammatory and fibrotic markers commonly observed in response to myocardial infarction and development of heart failure, we assessed the expression of mRNA for Tnfa, Il1b,Il6, Il18, Ccl2, Ccl3, Cxcl1, Cxcl2, Col1a1, Col3a1, Postn, and Tlr4 at 1 and 3 months." (PMID 35411847, 2022).
ischemic stroke (10 papers, 2015 to 2024). A stroke disorder caused by obstruction of blood flow to the brain, due to thrombotic (local blood clot formation) or embolic (due to a blood clot or other material traveling from another site) event. "Our research found that there is a previously unrecognized role and dynamic expression between Ccl3 and Lcp1 in basophils in the context of ischemic stroke, providing a new perspective for the synthesis of pathophysiological networks." (PMID 39931101, 2024). "Among the upregulated genes, Hspa1b, Ccl2, Cxcl2, Ccl3, Serpina3n, Timp1, H19, Hspb1, Ccl20, and Cxcl1 were found to demonstrate significant upregulation in pathological phase of ischemic stroke." (PMID 25861363, 2015). "The MCAO challenge itself induced a significant up-regulation of pro- and anti-inflammatory genes in the brains of both control and treatment animals, including IL-6, IL-1β, TNF-α, IL-10, CCL2, and CCL3, indicating a pivotal role of neuroinflammation in the pathology of acute ischemic stroke events." (PMID 30126083, 2018). "In summary, ischemic stroke results in upregulated expression of adhesion molecules (P‐selectin, E‐selectin, and ICAM‐1) and chemokines (CCL‐2, CCL‐3, CCL‐4, CCL‐5, and CXCL‐1)." (PMID 37122157, 2023). "Our results have revealed that ischemic stroke results in upregulated expression of adhesion molecules (P‐selectin, E‐selectin, and ICAM‐1) and chemokines (CCL‐2, CCL‐3, CCL‐4, CCL‐5, and CXCL‐1)." (PMID 37122157, 2023). "Macrophage inflammatory proteins (MIPs), MIP-1α (CCL3) and MIP-3α (CCL20), are also involved in inflammatory response after ischemic stroke." (PMID 31514749, 2019). "Ischemic stroke induces the release of different chemokines such as CCL-2, CCL-3, CCL-4, CCL7, CCL-11, CXCL-1, CXCL10, from the ischemic tissue." (PMID 30584250, 2018). "After ischemic stroke, TREM2-KO mice exhibit reduced microglial activity, with decreased transcription of pro-inflammatory cytokines TNFα, IL-1α, and IL-1β, as well as reduced transcription of chemokines CCL2 (MCP1), CCL3 (MIP1α), and chemokine receptor CX3CR1." (PMID 39649720, 2024).
lymphoma (10 papers, 2013 to 2024). A malignant (clonal) proliferation of B- lymphocytes or T- lymphocytes which involves the lymph nodes, bone marrow and/or extranodal sites. "Because GSE38885 included immunocompetent lymphomas and post-transplant lymphomas which were immunocompromised lymphoma patients, we isolated them to observe the expression level of CCL3." (PMID 36249005, 2022). "Here, we found that EBV mainly affects macrophages in IME of lymphoma patients through the differential gene CCL3." (PMID 36249005, 2022). "In accordance with its production by activated lymphoma cells, CCL3 is one of the most prominent cytokines with increased blood levels in CLL patients compared to healthy controls and dominates the cluster analysis of a comprehensive cytokine panel." (PMID 32899476, 2020). "In accordance with ibrutinib-sensitive cytokine production by activated lymphoma cells, the elevated blood levels of CCL3 and CCL4 in CLL patients show strong reduction upon ibrutinib treatment compared to other cytokines." (PMID 32899476, 2020). "Microarray profiling and cytokine array screening revealed that EBNA2 is associated with upregulation of the chemokines CCL3 and CCL4 in lymphoma cells." (PMID 28036258, 2017). "For example, bcl2 is an antiapoptotic factor upregulated by the EBV protein LMP1 during latency; ccl3 is a chemokine typically upregulated in lymphomas; and ccr7 is one of the first EBV-induced chemokine receptors documented." (PMID 26121143, 2015). "However, high expression of CCL3 was also found in EBV+ immunocompromised lymphomas (30 EBV+ and 10 EBV-)." (PMID 36249005, 2022). "To address this question, we validated eight plasma proteins (IL-17A, F5, FLT4, SFTPB, and GNPTG in lymphoma, TNFSF12, CCL3, and KIT in NSCLC) for response prediction and three plasma proteins (IL36G, SERPINC1, and LTA) for relapse monitoring." (PMID 38349411, 2024). "Five noninvasive biomarkers (FLT4, SFTPB, GNPTG, F5, and IL-17A) were further validated in an independent lymphoma cohort (n = 39), and another three noninvasive biomarkers (KIT, CCL3, and TNFSF1) were validated in NSCLC cohort (n = 76)." (PMID 38349411, 2024). "Therefore, maintained cytokine production in the presence of ibrutinib owing to the C481S mutation suggests that CCL3 and CCL4 may shape a supportive lymphoma microenvironment and thus contribute to in vivo selection of malignant B cells that express mutant BTK." (PMID 32899476, 2020). "Since EBV+ lymphomas secrete high quantities of CCL3, CCL4, CCL22, and CXCL10 compared to EBV- lymphoma lines, the high expression of CCR5, CCR4, and CXCR3 on both EBV VST groups may indicate complementary/alternate axes of migratory mechanisms." (PMID 39011042, 2024). "In addition, LOAd703-infected lymphoma cells upregulated the secretion of several chemokines (CXCL10, CCL17, CCL22, CCL3, CCL4) essential for immune cell homing, leading to enhanced CAR T-cell migration." (PMID 33666760, 2021). "Based on these findings, we propose that a pathway involving EBNA2/Btk/NF-κB/CCL3/CCL4 plays a key role in doxorubicin resistance, and therefore, inhibition of specific components of this pathway may sensitize lymphoma cells to doxorubicin." (PMID 28036258, 2017). "In addition, our results indicate that M2 macrophages induced an enrichment in FL cells of cytokines and chemokines that may attract other immunes populations, reshaping the lymphoma niche, such as CCL2 and CCL3 and IL-8, which may facilitate the recruitment of monocytes and neutrophils." (PMID 33731849, 2021).
meningitis (10 papers, 2006 to 2025). A disorder characterized by acute inflammation of the meninges of the brain and/or spinal cord. "Ccl3 and Cxcl10 expression induction was by trend less severe in Ac2-26-treated meningitis mice (p > 0.05; two-way ANOVA followed by Bonferroni test)." (PMID 33121515, 2020). "In infected WT mice, Streptococcus pneumoniae-induced meningitis lead to a robust and significant increase of Ccl3 and Cxcl10 expression levels." (PMID 33121515, 2020). "While the functions of many induced cytokines in C. neoformans infection remain not known, clinical investigations have demonstrated that CCL2 and CCL3 are induced in meningitis-forming patients." (PMID 31329596, 2019). "Intermediately, the EA ST28 strain MNCM43, which caused meningitis, induced a significant production of IL-1β, CCL2, and CCL3 only (p < 0.05)." (PMID 27409640, 2016). "Therefore, the combination of significant pleocytosis with elevated levels of inflammatory mediators, such as IL-1β, CCL2, and CCL3, may differentiate modest procedure-related sterile meningitis from an active infection." (PMID 31262978, 2019). "Concentrations of CCL3 and CCL4 in csf were not increased in any of the meningitis/encephalitis groups in comparison with controls and were not higher in csf than in serum, clearly not forming a chemotactic gradient towards cns." (PMID 26906062, 2016).
metabolic syndrome (10 papers, 2012 to 2024). A cluster of metabolic risk factors for CARDIOVASCULAR DISEASES and TYPE 2 DIABETES MELLITUS. "Higher LDL and lower HDL levels in patients with metabolic syndrome were associated with more ROS by the induction of oxidative NOX4 and NOX5 and more inflammatory molecules like MCP-1, C-C motif chemokine ligand 3 (CCL3 or MIP1α), and IL-8." (PMID 38132104, 2023). "Although elevation in circulatory and adipose expression of MIP-1α/CCL3 in metabolic syndrome is documented, the production and regulation of MIP-1α/CCL3 remains to be elucidated." (PMID 33050324, 2020). "CCL3 and AZGP1 showed two-fold higher and lower expression, respectively, in women with metabolic syndrome compared to women without metabolic syndrome." (PMID 23028366, 2012).
myocardial infarction (10 papers, 2013 to 2025). Gross necrosis of the myocardium, as a result of interruption of the blood supply to the area, as in coronary thrombosis. "Of particular note, the initial increase in Ccl3/Ccr5 and Il10 that we have noted at AC disease onset has also been observed in myocardial infarction." (PMID 32529556, 2020). "CCL3 levels were significantly elevated in patients with acute myocardial infarction (AMI) as compared with controls, as well as transiently elevated in UAP patients." (PMID 27573044, 2016). "CCL3 has been described to be upregulated after myocardial infarction, autoimmune myocarditis, and Chagas disease due to trypanosoma cruzi infection (Goseret al, 2005; Machadoet al, 2008; Alveset al, 2012)." (PMID 25193973, 2014). "Both CCL2 and CCL3 have been implicated in cardiac pathologies: CCL2 (MCP-1) is a well-known chemokine involved in recruitment of leukocytes and regulated after myocardial infarction (Birdsallet al, 1997)." (PMID 25193973, 2014). "Interestingly, IL-1, IL-6, CCL2, and CCL3 expression was reduced, whereas Arg1, IL4Rα, and IL-10 expression were increased in macrophages incubated with exosomes derived from the myocardial infarction group." (PMID 35548775, 2022). "For instance, higher CCL3 (and CCL5) concentrations were identified in patients with acute myocardial infarction as compared with controls." (PMID 27573044, 2016).
Anxiety (9 papers, 2016 to 2025). Intense feelings of nervousness, tension, or panic often arise in response to interpersonal stresses. "The early onset TSD mouse model Hexa−/−Neu3−/− mice demonstrated a high level of anxiety, along with elevated levels of Ccl2, Ccl3, Ccl4, Cxcl10." (PMID 39905541, 2025). "Our findings revealed significant upregulation of chemokines Ccl3, Ccl4, Ccl5 and the inflammatory mediator Cd86 in Asm KO-induced anxiety." (PMID 39905541, 2025). "In mice with Autism spectrum disorder, gut microbiota transplantation treatment significantly ameliorated anxiety-like and repetitive behaviors and reduced levels of chemokines including Ccl3 and Ccl5." (PMID 39905541, 2025). "Regression #2 shows that 45.4% of the variance in the pure_anxiety score was explained by IL-16 and IL-17 (both positively) and CCL3 (inversely)." (PMID 38538641, 2024).
chronic myeloid leukemia (9 papers, 2015 to 2022). "In the case of myeloid malignancies, chronic myeloid leukemia (CML) cells activate MSCs through soluble factors like CC motif ligand 3 (CCL3) or TPO, and by direct cell-cell contact causing overproduction of functionally altered OBs that do not support normal HSC maintenance." (PMID 32796596, 2020). "Severe osteoblastic defects were found in a model of myeloid blast-crisis chronic myeloid leukemia (CML, driven by BCR-ABL;Nup98/HoxA9), with decreased osteoprogenitors, endosteal-lining osteoblasts and bone mass, associated with increased CCL3 expression." (PMID 27436341, 2017). "In a mouse model of inducible BCR-ABL chronic myeloid leukemia (CML), leukemic cells stimulated MSC proliferation by a combination of soluble mediators (CCL3, TPO) and direct cell contact resulting in an overshooting production of early osteolineage cells." (PMID 32630305, 2020).
Cirrhosis (9 papers, 2016 to 2025). A chronic disorder of the liver in which liver tissue becomes scarred and is partially replaced by regenerative nodules and fibrotic tissue resulting in loss of liver function. "To support the CD8+ T cell expansion in aged cirrhosis we evaluated the concentration of CD8+ T cells recruiting chemokines CCL3 and CXCL10." (PMID 39656486, 2024). "Of the chemokines contributing to improved predictability of cirrhosis, CXCL10, CCL3, and CCL4 have been implicated in progression of liver disease." (PMID 36358697, 2022). "Excluding CCL-11, higher levels of chemokines CCL-3, CCL-4, CCL-5, CXCL-8, and CXCL-10 were observed in compensated cirrhosis patients compared to fibrotic and decompensated cirrhosis patients." (PMID 29977152, 2018). "In cases of HCC associated with MASLD-related cirrhosis, patients exhibited higher levels of fecal calprotectin and plasma levels of IL-8, IL-13, CCL3, CCL4, and CCL5 compared to those with MASLD-induced cirrhosis without HCC." (PMID 39451600, 2024).
epilepsy (9 papers, 2013 to 2025). A brain disorder characterized by episodes of abnormally increased neuronal discharge resulting in transient episodes of sensory or motor neurological dysfunction, or psychic dysfunction. "In this study, there was also a marked elevation in the levels of cytokines other than IL-1ra after epilepsy, including CCL3, IL-12p70, IL-13, IL-17, and bFGF." (PMID 37470000, 2023). "Some chemokine receptors, such as CCL3 and CCL11, are highly expressed in the hippocampus and are associated with epilepsy because they may promote the release of excitatory neurotransmitters." (PMID 37470000, 2023). "Indeed, inflammatory mediators may be relevant for the pathogenesis of epilepsy in FCD, as confirmed by the reported up-regulation of inflammatory cytokines and their receptors and/or downstream effectors (such as IL-1β, IL-6, CCL3, CCL4, STAT3, C-JUN and CCR5) in this disease." (PMID 35741692, 2022).
gout (9 papers, 2017 to 2024). A condition characterized by painful swelling of the joints, which is caused by deposition of urate crystals. "Compared with WT mice, St2-/- mice showed significantly reduced expression of IL-1β, IL-6, IL-13, CCL11, G-CSF, CXCL1, CCL2 and CCL3 proteins in ankle tissues, suggesting St2-/- mice showed generally attenuated inflammatory response during gout." (PMID 33204337, 2020). "Previous studies have found an increased expression of various chemokines (including CXCL8, CCL3, CXCL2, and MCP-1) in stimulations with MSU crystals in experimental models of gout or in the serum of gout patients." (PMID 36979628, 2023). "Nominally significant differences were observed for 7 proteins: TRAIL (TNF-related apoptosis-inducing ligand), DNER, IL-10, and CCL3 were reduced, and IL-6, RANKL (Receptor activator of nuclear factor kappa-Β ligand), and MCP-3 were elevated in samples of patients with tophaceous gout." (PMID 37810213, 2023). "We reason here that IL-33, after being released from macrophages, may act in an autocrine manner to induce CXCL1, CCL3 and IL-1β production via ST2 in macrophages during gout." (PMID 33204337, 2020).
lung disease (9 papers, 2010 to 2025). "It especially increased MIP1a/CCL‐3, which hones dendritic cells to drain lymph nodes and is important in lung diseases, including sarcoidosis." (PMID 38923221, 2024). "On the other hand it has been documented, that local production of IFN-γ as well as other proinflammatory cytokines (CCL3, CCL 11) in the lungs of mice infected with murine parainfluenza (Sendai Virus) correlated with severity of the lung disease." (PMID 25722655, 2015). "Recently elevated levels of CC chemokines MCP-1(CCL2), MIP-1α,(CCL3), MIP-1β and (CCL4) and MIP-3α (CCL20) were reported in BALF of young children with CF with little apparent lung disease or infection." (PMID 24216293, 2013).
myocardial ischemia (9 papers, 2019 to 2024). A disorder of cardiac function caused by insufficient blood flow to the muscle tissue of the heart. "These evidences indicated that Ccl3 is closely associated with myocardial ischemia." (PMID 31772617, 2019). "CCL3 attracts different leukocyte subsets, accelerates lesion formation, and is an independent predictor of future myocardial ischemia." (PMID 35211520, 2022). "In an animal model with early myocardial ischemia-reperfusion for 6 h, NRF2 was found to cooperate with Programmed Cell Death 4, promoting transcription initiation of C-C Motif Chemokine Ligand 3 (Ccl3) in myocardial tissues." (PMID 37047024, 2023). "In an animal model of myocardial ischemia, the expression of EGFR in alveolar macrophages was up-regulated, and contributed to the expression of proinflammatory cytokines (such as TNF, IL-6, IL-1β), chemokines (such CXCL2/MIP-2, MCP-1, and CCL3) and iNOS." (PMID 35095926, 2021).